IL1B (interleukin 1 beta)
Diseases named in the same sentence as IL1B in open-access papers (continued):
Sharing a sentence is not in itself a finding about the gene and the disease.
depression (continued). "In patients with depression, pathogen-associated molecular patterns (PAMPs) such as inducible nitric oxide synthase (iNOS) and nitric oxide (NO), and danger-associated molecular patterns (DAMPs) such as IL-1β and interleukin-18 (IL-18) enter the cytoplasm of hippocampal microglia." (PMID 39114351, 2024). "Therefore, the inhibition of IL-1β could serve as an accomplice in the management of UC-associated depression." (PMID 38393047, 2024). "In line with the immunometabolic hypothesis, studies have shown that genetic polymorphisms in inflammatory genes such as interleukin 1 beta (IL-1β), tumor necrosis factor alpha (TNFα) and C-reactive protein, influence depression incidence, severity, and treatment response." (PMID 35422688, 2022). "As an inhibitor of 5-LO, emodin prevented the depression behaviors along with a series of pathological changes in the hippocampus, such as hippocampal neuron and spine loss, microglial activation, increased IL-1β and TNF-α, and the activation of 5-LO and GSK3β." (PMID 34381778, 2021). "Also in line with hypotheses, the -511C allele in IL1β, previously associated with higher IL-1β expression, was associated with more severe depression following chronic interpersonal stress exposure, relative to T/T homozygotes." (PMID 25596176, 2015). "High-frequency keywords included depression, microglia, neuroinflammation, inflammation, hippocampus, metabolism, cytokines, IL-1β, lipopolysaccharide, stress, and anxiety." (PMID 41890205, 2026). "Patients with major depressive disorder (MDD) display elevated serum levels of IL‐1β and IL‐18, accompanied by increased expression of the NLRP3 inflammasome and caspase‐1." (PMID 41556446, 2026). "This study aimed to characterize structure-derived functional connectivity (FC) changes in BDII-D and to determine how dysconnectivity relates to depression severity and inflammatory markers, particularly interleukin (IL)-1β." (PMID 41928814, 2026). "Knockout of IL-1β in the hippocampus significantly reduces lipopolysaccharide (LPS)-induced anxiety and depression-like behavior." (PMID 40936908, 2025). "Elevated basal pro-inflammatory markers (e.g., IL-1β, IL-6) are typical in individuals vulnerable to depression, while resilience aligns with lower levels and immune-quiescent microglia." (PMID 41227125, 2025). "The polarization of microglia and the level of pro-inflammatory cytokines TNF-α, IL-1β, and IL-6 have been widely used to assess neuroinflammation in Alzheimer’s disease, major depression, ASD, and ADHD." (PMID 40429903, 2025). "Chronic mild stress (CMS) activates the NLRP3 inflammasome, enhances the maturation and release of IL-1β, and subsequently triggers neuroinflammation, ultimately leading to depression-like behavior." (PMID 40936908, 2025). "Several animal studies reported that depression-like behaviour in OVX animals was associated with NLRP3 inflammasome activation and enhanced IL-1β, IL-18, TLR4 and NF-κB expression in the hippocampus (Refs 153,163,164,165)." (PMID 40905280, 2025). "Chronic activation of pro-inflammatory cytokines, including tumor necrosis factor-alpha (TNF-α), interleukin-1 beta (IL-1β), and interleukin-6 (IL-6), is observed in both PH and depression." (PMID 39941652, 2025). "While the first point rightly emphasizes their pro-inflammatory M1-like activation and the production of excess IL-1β and TNF-α, which increase neuronal hyperexcitability and seizure susceptibility, their involvement in depression is equally important." (PMID 40941042, 2025). "The pro‐inflammatory factors such as TNF‐α, IL‐1β, and IL‐6 are classical markers of inflammation frequently studied in the context of depression." (PMID 40491976, 2025). "IL-1β was significantly elevated in postpartum women with depressive symptoms in two studies, suggesting its potential as a biomarker for detecting depression in postpartum women." (PMID 40682534, 2025).
depression (continued). "Another review examining the role of cytokines in adolescence found that IL-1β and TNF-α were associated with an increased risk of depression, and this relationship was influenced by neurodevelopment, hormonal changes, stress, and trauma." (PMID 39902492, 2025). "Meanwhile, it has been shown that mangiferin’s anti-inflammatory effects are mediated by blocking the NLRP3-inflammasome/caspase-1/IL-1β pathway, which is believed to have a role in the development of depression." (PMID 40696232, 2025). "Pro-inflammatory cytokines, such as IL-6, TNF-α, and IL-1β, are among the most studied biomarkers of inflammation in depression." (PMID 40004109, 2025). "According to network pharmacology results, IL-6, IL-1β, TNF-α, and IL-10 are closely associated with SD and depression." (PMID 40076470, 2025). "Compared to patients with bipolar disorder and the control cohort, IL-1B concentrations were significantly increased in patients with depression." (PMID 40313235, 2025). "A hallmark of depression is a heightened level of pro-inflammatory cytokines, including Tumor Necrosis Factor-α (TNF-α), Interleukin-6 (IL-6), and Interleukin-1β (IL-1β)." (PMID 41480347, 2025). "In animal models of depression, early-life stress significantly increased the expression levels of IL-1β, IL-6, and TNF-α in the brain, while blood levels remained unchanged." (PMID 41301474, 2025). "This, in turn, suppresses the activation of caspase-1 and decreases the production of IL-1β and IL-18, thereby improving mitochondrial energy metabolism and alleviating depression." (PMID 40699781, 2025). "It was observed that, compared to those with bipolar disorder and the control cohort, IL-1B concentrations were significantly increased in patients with depression (p=0.005)." (PMID 40313235, 2025). "In another study, researchers injected recombinant IL-1B into the murine hippocampus, and this resulted in elevated plasma glucocorticoid levels, which is more likely to induce depression in the presence of chronic stress." (PMID 40313235, 2025). "Research indicates that upon the activation of NLRP3, factors such as GSDMD, IL-1β, and IL-18 collectively contribute to the pathogenesis of depression." (PMID 41194915, 2025). "When NLRP3 is activated by stress, it regulates the activation of caspase-1, which in turn promotes the maturation of IL-1β in microglia, and the overproduction of cytokines in microglia contributes to the development of depression." (PMID 40308754, 2025). "A recent study reported that Phactr4 upregulation in the hippocampus in a chronic stress-induced depression model correlates with NF-kB induction and IL-1β secretion." (PMID 40462895, 2025). "The NLRP3 inflammasome, a key inflammatory signaling platform of the innate immune system, mediates the maturation and release of IL-1β and IL-18 and induces pyroptosis, playing a significant role in both depression and CVD." (PMID 41194915, 2025). "It has been shown that when microglia are activated, they release oxidative products and pro-inflammatory mediators such as TNF-α and IL-1β, which facilitate neuronal damage and contribute to depression." (PMID 40860146, 2025). "A mouse model of human depression and insomnia revealed damage to mitochondrial autophagy, decreased synthesis and secretion of melatonin, and elevated levels of IL-1β, NF-κB, Pink1, and Parkin in the pineal gland." (PMID 40943622, 2025). "For instance, genetic studies have linked specific polymorphisms in inflammatory pathways, such as variations in the IL-1β and TNF-α genes, to both IBD severity and susceptibility to depression." (PMID 40823034, 2025). "Previous studies have reported that microglia in the brains of depression patients exhibit abnormal activation, with significantly elevated expression levels of pro-inflammatory cytokines IL-1β, IL-6, and TNF-α." (PMID 41244868, 2025). "Relationship between the number of stressful life events and serum BDNF and IL-1β levels in patients with depression." (PMID 40904969, 2025).
depression (continued). "Ischemic injury post-AMI triggers an inflammatory cascade, with elevated pro-inflammatory cytokines (IL-1β, IL-6, TNF-α, sICAM-1), which have been linked to depression and anxiety." (PMID 40142595, 2025). "Research has shown that the excessive activation of pro-inflammatory cytokines, such as IL-1β, TNF-α, and IL-6, is closely associated with the pathogenesis of many central nervous system disorders, including depression." (PMID 40336842, 2025). "Our findings indicate that acupuncture can reduce TNF-α and IL-1β levels while increasing IL-10 and IL-4 levels in depression animals." (PMID 41244868, 2025). "Studies have found that compared to patients with epilepsy alone, those with comorbid depression exhibit higher peripheral blood levels of IL-1β, indicating a greater inflammatory burden in the dual-disease state." (PMID 40641625, 2025). "The regulation of the immune system, sleep, and circadian rhythms share common molecular mechanisms: IL-1β and TNF-α affect sleep and circadian rhythms to induce sleepiness, cognitive decline, depression, and fatigue, mimicking sleep loss symptoms." (PMID 40137863, 2025). "In terms of the outcome, this study primarily selected IL-1β, IL-6, and TNF-α as inflammatory biomarkers associated with depression." (PMID 41194929, 2025). "We found multiple deregulated genes involved in pain, such as TNF, IL1B, and IL6ST, were identified as being associated with both depression and suicide." (PMID 40313396, 2025). "Several investigations have examined the relationship between cytokines and depression, demonstrating that inhibiting cytokines, particularly IL-1β, can reduce depressive symptoms and enhance neurogenesis." (PMID 40904969, 2025). "Pro-inflammatory cytokine levels, including TNF-α, IL-6, and IL-1β, are continuously elevated in patients with AD, MS, and depression." (PMID 39861166, 2025). "Studies have consistently found that individuals with depression often exhibit elevated levels of inflammatory markers in their blood and cerebrospinal fluid, including cytokines such as IL-1β, IL-6, and TNF." (PMID 40065395, 2025). "The present study investigates the role of biological markers, specifically serum BDNF and IL-1β levels, in patients with depression compared to healthy controls." (PMID 40904969, 2025). "Lowered IL-1β levels are correlated with a decrease in depressive symptoms in individuals with major depressive disorder." (PMID 40371299, 2025). "Instead, depression showed a different neuroinflammatory response with lower IL-1β and higher IL-6 and IL-10 expression compared to the controls." (PMID 40179065, 2025). "Stress increases inflammatory cytokines (TNF-α, IL-1β, and IL-6), which disrupt neurotransmitter levels (serotonin, dopamine, and norepinephrine), contributing to disorders such as anxiety, depression, and neuroinflammation." (PMID 40309824, 2025). "Previous research has shown also that TNF-α and IL-1β disruption affects depression by hindering serotonin production and signaling, a crucial neurotransmitter for mood regulation." (PMID 39902492, 2025). "Among the key cytokines, interleukin (IL)-1β can interfere with neurotransmitter systems and trigger more inflammatory substances, while IL-6 often increases in people with depression, affecting the normal function of the hypothalamic–pituitary–adrenal axis." (PMID 40426956, 2025). "Studies have found the levels of IL-6, NF-κB, TNFα and IL-1β were increased in the blood and brain tissue with depression." (PMID 40308754, 2025). "The inhibitor MCC950 reduced NLRP3, IL-1β, and IL-18 levels in the hippocampus and improved depression behavior." (PMID 41048915, 2025). "The degree of psychopathological changes in patients with schizophrenia or depression was linked with the levels of the following pro-inflammatory cytokines: IFN-α, IFN-γ, IL-1β, IL-6, and TNF-α." (PMID 41010622, 2025).
depression (continued). "Hesperidin (20, 50, and 100 mg/kg orally for 28 days) reduces depression-like behaviors and expression of IL-1β, IL-6, TNF-α, NLRP3, caspase-1 in the prefrontal cortex and microglia in chronic unpredictable mild stress (CUMS)-induced rats." (PMID 40703750, 2025). "Interleukin-1beta (IL1b), cyclooxygenase 2 (COX-2), and prostaglandin E2 (PGE2) are increased and this increase is associated with an increase in depression-related behavior, as assessed in the forced swim test." (PMID 41155634, 2025). "When activated, the P2Y12 receptor in microglia promotes the expression of interleukin 1 Beta (IL-1β), which is a central factor in depression." (PMID 39859152, 2025). "The reversal of MBP/CNP deficits and IL-1β reduction suggests that myelin dysregulation in depression involves inflammatory-mediated oligodendrocyte impairment." (PMID 40500721, 2025). "In this study, we explored the relationship between HDRS scores, serum BDNF, and IL-1β levels in individuals with depression from the southern part of India." (PMID 40904969, 2025). "When ZEA 50 mg/kg was administered for 14 days, the levels of TNF-α and IL-1β in the hippocampus and subsided depression and anxiety symptoms were lowered." (PMID 40292259, 2025). "Evidence indicates that the NLRP3 inflammasome significantly contributes to the pathogenesis of depression by activating proinflammatory cytokines such as IL-1β and IL-18, which also play pivotal roles in the development of CVD." (PMID 41194915, 2025). "In patients with cancer as well as depression and fatigue, there are also elevated circulating inflammatory cytokines, and peripheral blood interleukin (IL)-1β, IL-6, tumor necrosis factor, and CRP levels show an increasing trend." (PMID 40966684, 2025). "The inflammatory cytokine levels in MDD patients remained lower than schizophrenia, yet IL-6 and IL-1β showed significant links to depression intensity." (PMID 40416228, 2025). "Our findings suggest that elevated serum IL-1β levels and reduced BDNF levels are associated with an increased likelihood of developing depression." (PMID 40904969, 2025). "Exogenous administration of lipopolysaccharide (LPS), a critical component of bacterial endotoxin, as well as cytokines like Interleukin-1β (IL-1β), have been widely used to establish rodent depression models for research use." (PMID 39791171, 2025). "In this study, OVX mice exhibited elevated serum CORT and IL-1β levels, consistent with neuroendocrine and inflammatory imbalance observed in depression." (PMID 41311824, 2025). "In recent years, the roles of pro-inflammatory cytokines (e.g., TNF-α, IL-1β) and anti-inflammatory cytokines (e.g., IL-4, IL-10) in the pathophysiology of depression have been increasingly clarified." (PMID 40453075, 2025). "The levels of interleukin-1 beta (IL-1β), interleukin-6 (IL-6), and tumor necrosis factor (TNF) are associated with anxiety behavior and also with more severe depressive disorders." (PMID 40563433, 2025). "In our study, XCHT was proven to alleviate depressive disorders by downregulation of IL‐1β, TNF‐α, and IL‐6 inflammasome, modulating the immune system by inhibiting Iba‐1 and GFAP overexpression, making it a promising candidate for the treatment of depression." (PMID 39981856, 2025). "Cytokines TNF-α and IL1β also impact the pathogenesis of weakness and pain, and as immune mediators, they indirectly affect the pathophysiological mechanism of depressive syndrome." (PMID 40699818, 2025). "Patients with anxiety and depressive disorders have increased levels of pro-inflammatory cytokines (e.g., TNFα, IL-1α, IL-1β, IL-4, IL-5, IL-6, IL-12, and interferon [IFN]-γ) and C-reactive." (PMID 39803412, 2025). "To confirm the presence of inflammation in rats with MI and depression, we quantified the levels of IL‐1β, IL‐18, and TNF‐α in rat serum using ELISA." (PMID 38970230, 2024).
depression (continued). "The pro-inflammatory cytokineinterleukin-1b (IL-1b) is induced in depressed patients, and depression iscorrelated with inflammation and reduced neurogenesis." (PMID 38954533, 2024). "Our present experiments provide further support for earlier research findings, which demonstrated that extracellular ATP (eATP) acts as a potent stimulus for the release of mature IL-1β from microglia, thus serving as a mediator for stress-induced depression." (PMID 38890305, 2024). "IL‐1β is a proinflammatory cytokine that plays a fundamental role in the emergence of depression‐like behavior." (PMID 39443283, 2024). "In elderly patients, increased serum levels of IL-1β and IL-6 in depression and increased levels of IL-1β, as well as microglial activation markers in AD, are reported." (PMID 38796643, 2024). "In a specific study, patients experiencing depression exhibited heightened levels of pro-inflammatory cytokines, including interleukin-1β (IL-1β) and tumor necrosis factor-α (TNF-α)." (PMID 38994205, 2024). "In human studies, elevated levels of IL-1β have been observed in individuals with major depressive disorder and other mood disorders." (PMID 38414751, 2024). "At 1 month after enrollment, the severity of depression was related to IL-1β (B 0.75, P = 0.04), IL-2 (B 1.41, P = 0.01) and IL-4 (B 0.91, P = 0.01)." (PMID 38459460, 2024). "There have been promising preclinical studies using polydatin in reducing UCMS-induced anxiety-like and depression-like behaviors and neuronal inflammatory changes including IL-1β levels." (PMID 38791125, 2024). "The increase in IL-1β can affect neurotransmitters and contribute to the activity of other neuroinflammatory pathways, thereby contributing to the pathogenesis of depression." (PMID 39343996, 2024). "After dividing the patients with depression into late-onset and early-onset groups, it was found that patients in the second group had the highest levels of IL-1β." (PMID 38575920, 2024). "Several treatments targeting the NLRP3 pathway attenuate chronic-stress-induced IL-1β levels and improve anxiety-like and depression-like behaviors." (PMID 38791125, 2024). "Elevated levels of other inflammatory cytokines such as Interleukin-1 beta (IL-1 β), Interleukin-2 (IL-2), and Interleukin-6 (IL-6) have also been observed in patients with major depressive disorder compared to healthy controls." (PMID 38959212, 2024). "In animal models of depression, increased levels of pro-inflammatory cytokines, such as IL-1β and TNF-α, and decreased levels of anti-inflammatory cytokines, such as IL-10 and TGF-β1, have been observed in the hippocampus and cortex." (PMID 38575920, 2024). "Song found that both EA and fluoxetine had an anti-inflammatory effect by reducing IL-1β in major depressive disorder patients." (PMID 38370556, 2024). "The RvD1, NLRP3, IL-1β, IL-18, and IL-4 serum levels were dynamically evaluated before and after 6-8-week anti-depression treatment." (PMID 38627683, 2024). "Elevated levels of pro-inflammatory cytokines such as interleukin-6 (IL-6), tumor necrosis factor-alpha (TNF-α), and interleukin-1 beta (IL-1β) are commonly observed in individuals with major depressive disorders and suicidal behavior." (PMID 39290301, 2024). "PSP demonstrated inhibitory effects on the upregulation of NLRP3, ASC, caspase-1, cleaved-caspase-1, and IL-1β in LPS-induced depression model in mice." (PMID 38389919, 2024). "In contrast, S-ketamine mitigates IL-1b–induced TNF-a, as well as IL-6–induced IL-1b and IL-8, highlighting the importance of considering ketamine formulation in depression treatment." (PMID 39297528, 2024). "Accordingly, specific medications can be selected based on the patient’s condition; for example, IL-1β is related to myocardial infarction, and downregulating its concentration with the demethylase Jmjd3 can improve post-infarction depression." (PMID 39329797, 2024).